EIF1AY (eukaryotic translation initiation factor 1A Y-linked)
Description:
Component of the 43S pre-initiation complex (43S PIC), which binds to the mRNA cap-proximal region, scans mRNA 5'-untranslated region, and locates the initiation codon. This protein enhances formation of the cap-proximal complex. Together with EIF1, facilitates scanning, start codon recognition, promotion of the assembly of 48S complex at the initiation codon (43S PIC becomes 48S PIC after the start codon is reached), and dissociation of aberrant complexes. After start codon location, together with EIF5B orients the initiator methionine-tRNA in a conformation that allows 60S ribosomal subunit joining to form the 80S initiation complex. Is released after 80S initiation complex formation, just after GTP hydrolysis by EIF5B, and before release of EIF5B. Its globular part is located in the A site of the 40S ribosomal subunit. Its interaction with EIF5 during scanning contribute to the maintenance of EIF1 within the open 43S PIC. In contrast to yeast orthologs, does not bind EIF1.
Synonyms: eIF-4C
Tractability: PROTAC: UniProt records ubiquitination sites on it; ubiquitination databases record sites on it.
Gene: Protein-coding gene on chromosome Y (20,575,694 to 20,593,154, forward strand). Ensembl gene ENSG00000198692.
Subcellular location: Cytoplasm
Subcellular location (Human Protein Atlas): Cytosol
Gene Ontology:
Molecular function: protein binding; translation initiation factor activity; RNA binding
Biological process: translational initiation
Cellular component: cytoplasm
Homologues: Orthologues: macaque EIF1AY (100% identical), chimpanzee EIF1AY (99% identical), pig EIF1AY (99% identical), tropical clawed frog eif1ax (99% identical), zebrafish eif1axb (99% identical), mouse Eif1a (98% identical), rat Eif1a (98% identical), zebrafish eif1axa (96% identical), mouse Eif1ad15 (94% identical), mouse Eif1ad10 (93% identical), mouse Eif1ad11 (93% identical), mouse Eif1ad12 (93% identical), and 15 more. Paralogues in human: EIF1AX (99% identical).
Diseases named in the same sentence as EIF1AY in open-access papers:
EIF1AY is named in the same sentence as 20 diseases in open-access papers, as found by Europe PMC text mining. Sharing a sentence is not in itself a finding about the gene and the disease. The quoted sentences say what the papers report.
heart failure (4 papers, 2018 to 2023). Inability of the heart to pump blood at an adequate rate to meet tissue metabolic requirements. "An expression profiling study based on new-onset heart failures caused by idiopathic dilated cardiomyopathy demonstrated that USP9Y, DDX3Y, RPS4Y1, and EIF1AY were significantly upregulated in male patients with high-fold changes." (PMID 29361784, 2018). "In addition, an expression profiling study based on new-onset heart failures demonstrated that DDX3Y, EIF1AY, and USP9Y are upregulated in male subjects." (PMID 36831031, 2023). "In accordance with adjusted p < 0.05 and |fold-change|>1.5, five RBPs (EIF1AY, RPS4Y1, DDX3Y, RNASE2, and CSDC2) were found in heart failure LV myocardium specimens in comparison to nonfailing controls." (PMID 36313471, 2022).
adenoma (1 paper, 2020). A neoplasm arising from the epithelium. "Several of these genes, e.g., EIF1AY, USP9Y, ZFY, TMSB4Y, have been used as gender-specific tissue biomarkers for both normal and tumoural tissues; corticotrope adenomas can now be added to the list of tissues presenting these markers of sexual dimorphism." (PMID 32183012, 2020).
asthma (1 paper, 2018). "The largest RIDM was detected for cg00063477, EIF1AY (+41%) and cg00061679, DAZ1, DAZ4 (-53%) when asthma was compared with controls." (PMID 30485264, 2018).
Azoospermia (1 paper, 2019). Absence of any measurable level of sperm,whereby spermatozoa cannot be observed even after centrifugation of the semen pellet. "Finally, the DDX3Y gene, along with KDM5D and EIF1AY, are azoospermia factors (AZFa)." (PMID 31817322, 2019).
coronary artery disease (1 paper, 2018). "This region is reportedly associated with coronary artery disease, and the up-regulation of specific genes within it (namely EIF1AY and USP9Y, as found in cc2) specifically linked with idiopathic heart failure." (PMID 29971234, 2018).
COVID-19 (1 paper, 2023). A disease caused by infection with severe acute respiratory syndrome coronavirus 2. "Examination of the top DEGs enriched and depleted in male versus female COVID-19 Mo/DCs revealed appropriate recovery of Y-linked genes (DDX3Y, EIF1AY, and UTY) and XIST, which enables X chromosome inactivation and, thus, is increased in female cells." (PMID 37606044, 2023).
glaucoma (1 paper, 2023). Increased pressure in the eyeball due to obstruction of the outflow of aqueous humor. "Database analysis revealed that seven host genes (NEAT1, SAMD12, KDM5D, ZFY, EIF1AY, TXLNGY, and DDX3Y) of nine DEcircRNAs were also differentially expressed in blood samples of patients with glaucoma, and the trend of differential expression of circRNAs and host genes was consistent." (PMID 37805546, 2023).
prostate tumors (1 paper, 2024). "A single DMR annotated to EIF1AY, located on the Y-chromosome, had a greater magnitude of increased methylation in prostate tumors of AA men (P < 0.05, represented as a dot below the second dashed line)." (PMID 38566104, 2024).
Sepsis (1 paper, 2024). Sepsis is defined as life-threatening organ dysfunction caused by a dysregulated host response to infection. "We performed a Mann-Whitney U test to evaluate the differential expression of the three genes (EIF1AY, APOBEC3B, and GUSBP3) in E. coli- and S. aureus-induced sepsis groups." (PMID 38968271, 2024).
Stroke (1 paper, 2015). Sudden impairment of blood flow to a part of the brain due to occlusion or rupture of an artery to the brain. "EIF1AY is on the Y chromosome and is overexpressed in men who have experienced a stroke." (PMID 25958224, 2015).
cancer (4 papers, 2016 to 2025). A tumor composed of atypical neoplastic, often pleomorphic cells that invade other tissues. "Moreover, several confirmed gender-related carcinogenic genes exhibit completely different distributions in male and female cancer samples, such as PIK3CA, NF1, EIF1AY, IGF1R, NRAS, KDM5D, UTY, and PPP6C." (PMID 39541191, 2024). "There was a very high-degree of commonality across all the models, with three Y-chromosome genes selected across all 17 cancers (ZFY, EIF1AY, and DDX3Y), RPS4Y1 (also on the Y-chromosome) selected across 15 of 17 cancers, and XIST (on the X-chromosome) selected across 14 of 17 cancers." (PMID 26755347, 2016).
tumour (2 papers, 2020 to 2024). "The expression of EIF1AY and KDM5D was elevated in tumour samples but almost absent in normal pituitary tissue." (PMID 39548559, 2024).
immune diseases (1 paper, 2014). "We thus presume that the upregulated DEGs such as Cav1, CD200R1, TNFRSF17 and CXCR3 and downregulated DEGs such as EIF1AY and DDX3Y in healthy female may be involved in gender predominance of some immune diseases." (PMID 24741625, 2014). "Moreover, the upregulated DEGs (Cav1, CD200R1, TNFRSF17, and CXCR3) and downregulated DEGs (EIF1AY and DDX3Y) in healthy female may be involved in gender predominance of some immune diseases." (PMID 24741625, 2014).
EIF1AY also shares sentences with these, for which no sentence is quoted: idiopathic dilated cardiomyopathy (2 papers); melanoma (2); acute myeloid leukemia (1); benign prostatic hyperplasia (1); gastric cancer (1); liver cancer (1); lung carcinoma (1).